PPP1R26 (protein phosphatase 1 regulatory subunit 26)
Description:
Inhibits phosphatase activity of protein phosphatase 1 (PP1) complexes. May positively regulate cell proliferation.
Synonyms: KIAA0649; NRBE3
Tractability: PROTAC: ubiquitination databases record sites on it.
Gene: Protein-coding gene on chromosome 9 (135,479,073 to 135,488,897, forward strand). Ensembl gene ENSG00000196422.
Subcellular location: Nucleus, nucleolus
Subcellular location (Human Protein Atlas): Nucleoplasm
Gene Ontology:
Molecular function: protein binding; protein phosphatase inhibitor activity
Cellular component: nucleoplasm; nucleolus
Genetic constraint (gnomAD): Loss-of-function variants: 22 observed, 60.95 expected, observed/expected ratio (o/e) 0.36, 90% interval 0.26 to 0.51. The upper end of that interval is the gene's LOEUF score, 0.51, which puts it in group 2 of 6, group 1 being the genes least tolerant of losing a copy. Missense variants: 1,599 observed, 1,619.6 expected, observed/expected ratio (o/e) 0.99, 90% interval 0.95 to 1.03. Synonymous variants: 729 observed, 697.18 expected, observed/expected ratio (o/e) 1.05, 90% interval 0.98 to 1.11.
Homologues: Orthologues: chimpanzee PPP1R26 (98% identical), macaque PPP1R26 (92% identical), guinea pig PPP1R26 (63% identical), pig PPP1R26 (59% identical), rat Ppp1r26 (56% identical), mouse Ppp1r26 (56% identical), tropical clawed frog ppp1r26 (25% identical), zebrafish ppp1r26 (16% identical).
Diseases named in the same sentence as PPP1R26 in open-access papers:
PPP1R26 is named in the same sentence as 5 diseases in open-access papers, as found by Europe PMC text mining. Sharing a sentence is not in itself a finding about the gene and the disease. The quoted sentences say what the papers report.
thyroid cancer (1 paper, 2023). "We found five TAD blocks with CoMut genes/events specific to ATC with certain mutation frequency in The Cancer Genome Atlas Thyroid Cancer (TCGA-THCA) cohort, including CoMut pairs MAST/NSUN4, AM129B/TRUB2, COL5A1/PPP1R26, PPP1R26/GPSM1/CCDC183, and PRAC2/DLX4." (PMID 36609218, 2023).
tumor (3 papers, 2013 to 2023). "PPP1R26 (protein phosphatase 1 regulatory subunit 26) has been associated with tumour formation and has been observed to be upregulated in various malignancies." (PMID 36653562, 2023). "PPP1R26 is localized in the nucleus in tumor cells and upregulated in the HCC tumor tissues compared with their non-tumorous counterparts." (PMID 35292107, 2022). "In the present study, we found that the expressions of both PTBP1 and PPP1R26 were upregulated in human HCC tumor tissues." (PMID 35292107, 2022). "Analysis of a 424-case cohort from The Cancer Genome Atlas (TCGA) database also showed that the expression of PPP1R26 is significantly upregulated in tumor tissues compared with adjacent normal tissues." (PMID 35292107, 2022). "Univariate Cox regression analysis revealed that the PPP1R26 expression level, tumor number, microscopic vascular invasion, Edmondson-Steiner grade, BCLC stage and AFP level were the significant prognostic indicators in HCC (P < 0.05, respectively)." (PMID 35292107, 2022). "Targeting PPP1R26 reduces the glycose metabolism and the acidification rate in HCC to devoid the favorable condition for tumor proliferation and metastasis." (PMID 35292107, 2022). "Our findings demonstrate that glycolysis and EMT are simultaneously activated by upregulation of PPP1R26 to drive tumor progression in HCC, and provide PPP1R26 as a potential therapeutic target in HCC." (PMID 35292107, 2022). "Furthermore, depletion of PPP1R26 by shRNA dramatically inhibits tumor growth in mouse xenografts in vivo, demonstrating that small molecules targeting PPP1R26 such as siRNA or chemical compound may provide a potential therapeutic strategy in the HCC treatment." (PMID 35292107, 2022). "GFP-PTBP1 restored the tumor volume and tumor weight reduced by PPP1R26-shRNA, revealing that overexpression of PTBP1 restores the tumorigenesis reduced by PPP1R26 depletion." (PMID 35292107, 2022). "The expressions of PPP1R26, PTBP1 and PKM2 were upregulated in 93.8% (15/16), 100% (16/16) and 93.8% (15/16) in human HCC tumor tissues compared with the non-cancerous tissues, respectively." (PMID 35292107, 2022).
cancer (2 papers, 2022 to 2023). A tumor composed of atypical neoplastic, often pleomorphic cells that invade other tissues. "The degree of staining for GPX3 and PPP1R26 was stronger in normal tissues than in cancer tissues; on the other hand, ZFYVE27 showed the opposite trend." (PMID 36717783, 2023). "Most of these CAF-related genes are associated with tumorigenesis and cancer progression, including GLT8D1, GPX3, NRP1, PPP1R26, SERPINE1, and TMSB15A." (PMID 36717783, 2023). "To unravel the function of PPP1R26 in cancer cell metabolism, we performed bioinformatics analysis using the TCGA LIHC dataset." (PMID 35292107, 2022).
PPP1R26 also shares sentences with these, for which no sentence is quoted: hepatocellular carcinoma (1 paper); viral infection (1).